HPDL (4-hydroxyphenylpyruvate dioxygenase like)
Description:
Iron-dependent dioxygenase that catalyzes the conversion of 4-hydroxyphenylpyruvate (4-HPPA) to 4-hydroxymandelate (4-HMA) in the mitochondria, one of the steps in the biosynthesis of coenzyme Q10 from tyrosine.
Synonyms: GLOXD1; MGC15668; 4-HPPD-L; NEDSWMA; SPG83
Tractability: PROTAC: ubiquitination databases record sites on it.
Gene: Protein-coding gene on chromosome 1 (45,326,895 to 45,328,710, forward strand). Ensembl gene ENSG00000186603.
Subcellular location: Mitochondrion
Subcellular location (Human Protein Atlas): Mitochondria; Nucleoplasm
Pathways (Reactome):
Metabolism: Ubiquinol biosynthesis
Gene Ontology:
Molecular function: 4-hydroxymandelate synthase activity; 4-hydroxyphenylpyruvate dioxygenase activity; oxidoreductase activity, acting on single donors with incorporation of molecular oxygen
Biological process: aromatic amino acid metabolic process
Cellular component: mitochondrion; mitochondrial matrix
Genetic constraint (gnomAD): Loss-of-function variants: 8 observed, 12.2 expected, observed/expected ratio (o/e) 0.66, 90% interval 0.38 to 1.18. The upper end of that interval is the gene's LOEUF score, 1.18, which puts it in group 5 of 6, group 1 being the genes least tolerant of losing a copy. Missense variants: 530 observed, 458.53 expected, observed/expected ratio (o/e) 1.16, 90% interval 1.08 to 1.24. Synonymous variants: 250 observed, 211.33 expected, observed/expected ratio (o/e) 1.18, 90% interval 1.07 to 1.31.
Gene-disease validity (ClinGen):
ClinGen rates the evidence that HPDL causes each of these diseases.
Leigh syndrome (autosomal recessive): Moderate. A progressive neurological disease defined by specific neuropathological features associating brainstem and basal ganglia lesions.
Homologues: Orthologues: chimpanzee HPDL (99% identical), macaque HPDL (95% identical), dog HPDL (84% identical), rabbit HPDL (84% identical), pig HPDL (82% identical), rat Hpdl (80% identical), guinea pig HPDL (79% identical), mouse Hpdl (79% identical), zebrafish HPDL (43% identical), tropical clawed frog hpdl (41% identical), Caenorhabditis elegans C31H2.4 (25% identical). Paralogues in human: HPD (25% identical).
Diseases named in the same sentence as HPDL in open-access papers:
HPDL is named in the same sentence as 44 diseases in open-access papers, as found by Europe PMC text mining. Sharing a sentence is not in itself a finding about the gene and the disease. The quoted sentences say what the papers report.
pancreatic ductal adenocarcinoma (6 papers, 2020 to 2025). An infiltrating adenocarcinoma that arises from the epithelial cells of the pancreas. "The three-dimensional growth of cell lines associated with pancreatic ductal adenocarcinoma (PDAC) is influenced by HPDL, a protein found in the intermembrane space of mitochondria." (PMID 38451188, 2024). "High expression of HPDL in pancreatic ductal adenocarcinoma is predictive of poorer prognosis and immunosuppression in the patients." (PMID 40173324, 2025). "HPDL, a protein situated in the mitochondrial intermembrane space, mechanistically influences the three-dimensional growth of pancreatic ductal adenocarcinoma (PDAC) cell lines and promotes the proliferation of MIAPACA2 orthotopic xenografts." (PMID 38451188, 2024). "Meanwhile, HPDL supports tumorigenesis in pancreatic ductal adenocarcinoma in a glutamine metabolism-dependent manner." (PMID 35265521, 2022). "In this study, we show that 4-hydroxyphenylpyruvate dioxygenase-like protein (HPDL), a previously uncharacterized protein, is positively associated with the development of pancreatic ductal adenocarcinoma (PDAC) and disease prognosis." (PMID 33537239, 2020).
hereditary spastic paraplegia (5 papers, 2024 to 2026). Hereditary spastic paraplegias (HSP) comprise a genetically and clinically heterogeneous group of neurodegenerative disorders characterized by progressive spasticity and hyperreflexia of the lower limbs. "Similar reports identified HPDL variants in patients with a broader phenotypic spectrum with severe to mild disease, including a form of adolescent‐onset hereditary spastic paraparesis (SPG83; MIM# 619027)." (PMID 40368591, 2025). "Recently, a mitochondrial encephalopathy due to biallelic HPDL variants was described, associated with a broad range of clinical manifestations ranging from severe, infantile‐onset neurodegeneration to adolescence‐onset hereditary spastic paraplegia." (PMID 40368591, 2025). "However, the phenotypic spectrum can be so broad as to limit recognition of allelic disorders, e.g., biallelic HPDL variants associating with Leigh syndrome on the severe end of the spectrum and simple hereditary spastic paraplegia on the mild end." (PMID 38244259, 2024). "As biallelic pathogenic variation in HPDL causes mitochondrial neurodevelopmental disorders ranging from Leigh syndrome to simple hereditary spastic paraplegia, supplementation of CoQ10 or 4-HMA might have therapeutic benefit in these conditions." (PMID 38244259, 2024). "Biallelic variants in HPDL cause a mitochondrial neurodevelopmental disease spectrum ranging from neonatal mitochondrial encephalopathy and Leigh syndrome to adolescent-onset, isolated hereditary spastic paraplegia (HSP)." (PMID 38244259, 2024).
pancreatic cancer (3 papers, 2020 to 2025). "In addition, HPDL plays a crucial role in the poor prognosis and development of pancreatic cancer, by regulating glutamine metabolism and influencing redox balance." (PMID 37333498, 2023). "The overexpression (OE) model was generated in PaTu 8988t due to its relatively low expression among other pancreatic tumor cell lines, which may imitate the functional effect of HPDL." (PMID 33537239, 2020). "Apart from GSEA, we also found 23 DEGs in the pancreatic cancer pathway of KEGG, including 17 oncogenes and 5 tumor suppressor genes, demonstrating the promotive effect of HPDL on PDAC." (PMID 33537239, 2020). "To further investigate HPDL in PDAC, we generated two cell models in pancreatic tumor cell lines." (PMID 33537239, 2020).
cutaneous melanoma (2 papers, 2022 to 2023). A primary melanoma arising from atypical melanocytes in the skin. "However, four genes, i.e., HPDL, GRIPAP1, GBP2, and TRIM34, have been reported to exhibit prognostic significance with respect to melanoma for the first time, while HAPLN3, CCL8, FCGR2A, and IFITM1 have been reported to relate with the initiation and immune microenvironment of cutaneous melanoma." (PMID 36818162, 2023).
melanoma (2 papers, 2023 to 2024). A malignant, usually aggressive tumor composed of atypical, neoplastic melanocytes. "In the melanoma group GSE78220, individuals exhibiting reduced HPDL levels had a higher likelihood of survival than those with elevated HPDL expression." (PMID 38451188, 2024). "We next investigated the correlation between HPDL expression levels and the response to anti-PD-L1 immunotherapy in a pan-cancer cohort, including bladder cancer and the expression levels of anti-PD1 in melanoma." (PMID 38451188, 2024).
microcephaly (2 papers, 2024 to 2025). A congenital or acquired developmental disorder in which the circumference of the head is smaller than normal for the person's age and sex. "4‐Hydroxyphenylpyruvate dioxygenase like (HPDL/SPG83) biallelic mutation leads to a range of neurological phenotypes, which included spastic tetraplegia, microcephaly, brain atrophy, epilepsy, and severe intellectual and motor disability." (PMID 39932116, 2025). "Finally, another example is SPG83, causing symptoms ranging from microcephaly and severe intellectual disability to pure late-onset HSP caused by biallelic variants in HPDL." (PMID 38473862, 2024).
Mitochondrial encephalopathy (2 papers, 2024 to 2025). "Recently, biallelic variants in HPDL (4‐hydroxyphenylpyruvate dioxygenase‐like) were identified as causes of a rare mitochondrial encephalopathy (ME), associated with a broad range of clinical manifestations, from severe, infantile‐onset neurodegeneration to pure or complex spastic paraplegia." (PMID 40368591, 2025).
Spastic paraplegia (2 papers, 2023 to 2025). Complete loss of the ability to move the lower limbs accompanied by spasticity of the lower limbs. "In line with the idea that HPDL is a CoQ10 biosynthesis enzyme, the clinical manifestation of HPDL deficiency ranges from early-onset encephalopathy up to adolescent-onset spastic paraplegia." (PMID 36978966, 2023).
Spastic tetraplegia (2 papers, 2025). Spastic paralysis affecting all four limbs. "Further, biallelic variants in the HPDL gene have been shown to cause a mitochondrial disease associated with neurological manifestations, as a syndrome varying from juvenile-onset pure HSP to infantile-onset spastic tetraplegia associated with global developmental delays." (PMID 41153514, 2025).
CNS lymphoma (1 paper, 2021). "Previous studies have found that HPDL exhibits differential expression in CNS lymphoma compared with nonprimary central nervous system (CNS) lymphoma." (PMID 34557230, 2021).
Epileptic encephalopathy (1 paper, 2023). A condition in which epileptiform abnormalities are believed to contribute to the progressive disturbance in cerebral function. "In one of the individuals, a patient with epileptic encephalopathy and a family history of long QT and with a previously identified KCNQ1 pathogenic variant, we also identified an HPDL causative variant [p.(Ala116Cysfs*81)], leading to a dual diagnosis." (PMID 37152996, 2023).
Exotropia (1 paper, 2025). A form of strabismus with one or both eyes deviated outward. "In this case report, we present a case of a nine-year-old girl with exotropia with a novel HPDL variant who underwent strabismus surgery." (PMID 40432646, 2025).
Leukoencephalopathy (1 paper, 2023). This term describes abnormality of the white matter of the cerebrum resulting from damage to the myelin sheaths of nerve cells. "Another brain pathology observed in individuals with COQ defects is disturbed myelination and leukoencephalopathy (PDSS1, COQ2, COQ6, COQ7 and HPDL)." (PMID 36978966, 2023).
lung adenocarcinoma (1 paper, 2024). A carcinoma that arises from the lung and is characterized by the presence of malignant glandular epithelial cells. "We observed a notable correlation between HPDL expression and a variety of infiltrating immune cells, including macrophages, B cells, cancer-associated fibroblasts (CAFs), and CD8+ T cells, in lung adenocarcinoma (LUAD), thymic carcinoma (THYM), and testicular germ cell tumors (TGCTs)." (PMID 38451188, 2024).
neuroblastoma (1 paper, 2026). Neuroblastoma (NB) is the most common solid, extracranial childhood tumor. "Starting from mutant neuroblastoma cells, we demonstrated that HPDL is important to respiratory chain supercomplex assembly and cellular redox balance." (PMID 41720761, 2026). "Mitochondrial morpho-functional characterization in mutant neurons confirmed disruption of OxPhos chain functionality in neuroblastoma knock-out model cells and HPDL mutant cortical progenitors also displayed defects in respirasome assembly and increased ROS generation rate." (PMID 41720761, 2026).
ovarian carcinoma (1 paper, 2024). A malignant neoplasm originating from the surface ovarian epithelium. "PKM2, MRPS12, NDUFC2, HPDL, MRPL14, COA6 and RNF144B were significantly upregulated in ovarian cancer, but the down-regulation of NDUFC2, HPDL, MRPL14, COA6 and RNF144B was associated with poor prognosis in patients with ovarian cancer." (PMID 39478854, 2024). "PKM2, MRPS12, NDUFC2, HPDL, MRPL14, COA6 and RNF144B were significantly upregulated in ovarian cancer tissues than in normal tissues (P < 0.05), while RPL23, FGFR1OP2, CAPN10, ALDH1L1 and ACSM1 were significantly down-regulated (P < 0.05)." (PMID 39478854, 2024).
Strabismus (1 paper, 2025). A misalignment of the eyes so that the visual axes deviate from bifoveal fixation. "Further ophthalmological findings in cases with HPDL gene variants are necessary to elucidate the pathogenesis of strabismus." (PMID 40432646, 2025). "Regarding the ophthalmological findings of HPDL variants, nine cases (52.9%) were noted to have visual impairment and strabismus was noted in 17 participants, and among 31 participants, 11 cases (35.5%) had ocular motility disorder." (PMID 40432646, 2025). "Our results provide important information for the associations of variant in HPDL with progressive spastic paraplegia, strabismus and retinal changes and broaden the genetic spectrum of HPDL-related disease." (PMID 40432646, 2025). "Because it is a novel HPDL variant, it is not exactly clear how this frameshift was involved in strabismus and retinal changes." (PMID 40432646, 2025). "The exact incidence of strabismus associated with HPDL variants is not clear, and its mechanism is unknown." (PMID 40432646, 2025).
tumor (9 papers, 2015 to 2026). "At last, the key PAG that constitute the risk model, HPDL, was found to be significantly positively correlated with tumor stemness." (PMID 36818162, 2023). "Understanding the function of HPDL in tumor immunity and its impact on the advancement of cancer immunotherapies can be facilitated by these valuable data." (PMID 38451188, 2024). "Further experiments are necessary to clarify the HPDL mechanism’s impact on tumor occurrence and progression simultaneously." (PMID 38451188, 2024). "We also validated the differential expression of LY6D and HPDL using Western blot analysis, which confirmed that they were expressed at higher levels in tumor tissues." (PMID 37274269, 2023). "Overexpression of HPDL promotes tumorigenesis and protects tumor cells from oxidative stress by reprogramming the metabolic profile of PDAC cells toward glutamine metabolism." (PMID 35359394, 2022). "Because serum contains a certain amount of DNA derived from lysed tumor cells, the methylation status of HPDL was detected in the serum of 60 CRC patients, 30 CA patients and 33 healthy controls." (PMID 34965217, 2021). "Collectively, HPDL is upregulated in PDAC at both the mRNA and protein levels, in both tumor cell lines and tumor tissues, and high expression of HPDL is associated with poor prognosis in PDAC patients." (PMID 33537239, 2020). "To investigate this, we analyzed the genetic alterations of HPDL in TCGA Pancancer tumor samples." (PMID 38451188, 2024). "Additionally, representative cases consisting of 20 CRC, 10 CA patients and 10 healthy controls were selected to detect HPDL methylation status in serum and colorectal normal or tumor tissue from the same patient." (PMID 34965217, 2021). "Overall, our results found that HPDL regulates redox balance via a glutamine-dependent antioxidative pathway, which may be the key event in explaining the positive effect on tumor proliferation of HPDL." (PMID 33537239, 2020).
cancer (5 papers, 2021 to 2025). A tumor composed of atypical neoplastic, often pleomorphic cells that invade other tissues. "In the IMvigor210 cancer cohort, it was found that a decrease in HPDL expression was associated with a favorable prognosis and improved response to anti-PD-L1 immunotherapy." (PMID 38451188, 2024). "To uncover the biological mechanisms associated with HPDL expression in cancer, we conducted a comparative examination of gene expression." (PMID 38451188, 2024). "GSEA revealed the cancer characteristics associated with HPDL expression." (PMID 38451188, 2024). "HPDL is expressed excessively in a wide variety of cancer types, indicating its prognostic and predictive value." (PMID 38451188, 2024). "The examination involved comparing the subset that exhibited elevated HPDL levels to the subset that displayed low HPDL levels, with a particular emphasis on distinct forms of cancer." (PMID 38451188, 2024). "This further emphasizes the significance of conducting additional research on the function of HPDL in the infiltration of immune cells and its potential consequences for cancer treatment and immunotherapy." (PMID 38451188, 2024). "Our study establishes HPDL as a significant prognostic marker in clinical settings, indicating its utility not only in predicting cancer prognosis but also the efficacy of immunotherapies, thereby highlighting its potential as a target for immunotherapy." (PMID 38451188, 2024). "Enhancing our comprehension of the function of HPDL in cancer immunotherapy holds the possibility of enhancing patient outcomes." (PMID 38451188, 2024). "To clarify the patterns of HPDL expression in different types of cancer, we combined TCGA databases and performed a comprehensive analysis on the levels of HPDL mRNA expression in a diverse range of malignant diseases." (PMID 38451188, 2024). "After analyzing the previous results, we assessed the prognostic significance of HPDL in cancer patients who underwent ICI treatment." (PMID 38451188, 2024). "According to the results, HPDL plays a vital role in predicting the future prospects of cancer patients and is expected to become a powerful indicator for the prognosis of cancer patients in the future." (PMID 38451188, 2024). "The findings suggest that HPDL is likely involved in the advancement and outlook of cancer through its interaction with the microenvironment of the disease." (PMID 38451188, 2024). "In addition, the correlation analysis between HPDL and the pan-cancer immunomodulatory factors indicates that the HPDL expression was highly correlated to the expression of specific immunomodulatory genes, especially in CHOL, UVM, MESO, PCPG, and DLBC." (PMID 38451188, 2024). "Considering the abnormal expression of HPDL in cancer, our hypothesis is that genetic changes in HPDL might play a role in this occurrence." (PMID 38451188, 2024). "The results emphasize the intricate connection between HPDL expression and the infiltration of immune cells in various types of cancer, indicating that HPDL might have a role in regulating the immune microenvironment of tumors." (PMID 38451188, 2024). "Observing the aberrant expression of HPDL in cancer led us to hypothesize that genetic alterations in HPDL might be responsible for this phenomenon." (PMID 38451188, 2024). "The data validate HPDL’s capacity to anticipate the response to immunotherapy and propose that HPDL may serve as a valuable marker for cancer immunotherapy." (PMID 38451188, 2024). "The results suggest that HPDL might have different roles in different types of cancer." (PMID 38451188, 2024). "Moreover, HPDL can function as a predictive marker for specific inhibitors in instances of cancer." (PMID 38451188, 2024). "We cannot state, at this point in our research, that the death of cancer cells was associated with the high level of media alkalization for the t440 wires, as the extracts from these wires did not much affect the growth of normal hPDL." (PMID 34772199, 2021).
cancer (continued). "According to the information obtained from the HPA database, analysis of immunofluorescence (IF) images revealed that the HPDL protein predominantly resided in the nucleoplasm of the MCF7, U20S, and CAC02 cancer cell lines." (PMID 38451188, 2024).
HPDL also shares sentences with these, for which no sentence is quoted: breast carcinoma (3 papers); Acute encephalopathy (1); Alzheimer disease (1); bladder cancer (1); Brain atrophy (1); developmental delays (1); Encephalopathy (1); endometrial cancer (1); epilepsy (1); Huntington disease (1); Intellectual disability (1); Leigh syndrome (1); metabolic disease (1); mitochondrial disease (1); movement disorder (1); neurodegenerative disease (1); neurodevelopmental disorder (1); neurological disorder (1); non-small cell lung carcinoma (1); nonalcoholic fatty liver disease (1); papillary thyroid cancer (1); Parkinson disease (1); testicular germ cell tumor (1); thymic carcinoma (1); Wernicke encephalopathy (1).